ENSG00000212149
Synonyms: LOC124900400
Gene: Small nucleolar RNA gene on chromosome 17 (42,940,575 to 42,940,702, reverse strand). Ensembl gene ENSG00000212149.
Gene Ontology:
Biological process: RNA processing
Cellular component: nucleolus
Homologues: Paralogues in human: SNORA40B (97% identical), SNORA40 (94% identical), SNORA40C (91% identical).